PTK7 (protein tyrosine kinase 7 (inactive))
Diseases named in the same sentence as PTK7 in open-access papers (continued):
Sharing a sentence is not in itself a finding about the gene and the disease.
cancer (continued). "Given the significant roles of Wnt signaling and VEGF signaling in cancer, there is an increasing interest in exploring the role of PTK7 in cancer." (PMID 39474113, 2024). "Beyond the genetic and functional interactions observed between PTK7 and other WNT/PCP genes during embryogenesis, PTK7 modulates WNT/PCP receptors in cancer cells." (PMID 38773263, 2024). "For example, the aptamers that selectively bind to the protein tyrosine kinase 7 (PTK7)—the cancer marker that is localized in the membrane of various cancer cells—were used to detect leukemic cells using electrochemical and acoustic methods." (PMID 36832017, 2023). "It is increasingly known that cancer invasion and metastasis fundamentally rely on collective migration and that PTK7 is required in this process." (PMID 37212485, 2023). "We targetedprotein tyrosine kinase 7 (PTK7), a prominent cancer marker, and demonstratedaptamer-mediated biotin transfer to specific lysine residues on theextracellular domain of the protein." (PMID 37473438, 2023). "Agents that block the function of PTK7, such as a PTK7-neutralizing antibody, are likely to be an effective treatment with reduced side effects for PTK7-positive cancers such as BC, since they act only on cells in which PTK7 functions." (PMID 37569547, 2023). "POSTN+ CAF-derived POSTN promotes the cancer stem cell (CSC) phenotype of HNSCC by activating protein tyrosine kinase 7 (PTK7)-Wnt/β-Catenin signaling through binding to PTK7 in cancer cells." (PMID 37143134, 2023). "Despite being catalytically defective, PTK7 is expressed in various carcinoma types, particularly in BC and TNBC." (PMID 37569547, 2023). "The protein tyrosine kinase 7 (PTK7) has been recently shown to mediate the crosstalk between the tumor cells and CAFs and to promote cancer stemness in head and neck cancer." (PMID 35919862, 2022). "The expression of PTK7, which is upregulated in various malignancies, is negatively correlated with disease-free survival and/or overall survival in patients with cancer." (PMID 36139622, 2022). "We and others have shown that PTK7 is involved in the promotion of adhesion, wound healing, and migration in various cancers including ESCC." (PMID 36293051, 2022). "PTK7 transcriptomic levels were also increased in primary tumors compared to normal tissues of these commonly occurring cancers." (PMID 35977930, 2022). "The cancer cell-binding Sgc8c aptamer was used as the identification unit for PTK7-positive target cancer cells, while HRP-like DNAzyme was applied as the probing component to generate ABTS-related colorimetric signals." (PMID 36195928, 2022). "Several studies have been conducted to treat cancers by targeting PTK7 or to predict the prognosis of tumors based on the degree of PTK7 expression." (PMID 36293051, 2022). "PTK7 high-expression has been reported in several cancers, and it has important signaling functions in the cancer development and progression." (PMID 36471380, 2022). "From this study, we evaluated the potential of PTK7 mAbs as anticancer agents for the treatment of PTK7-positive cancers, including ESCC." (PMID 36293051, 2022). "As PTK7 is reported to be involved in oncogenesis and angiogenesis, it is a potential therapeutic target for cancer and vascular diseases." (PMID 36139622, 2022). "Our study describes how PTK7 expression provides a niche for cancer cells to sustain tumorigenesis, and highlights this molecule as a candidate target to improve the therapeutic outcome in OC." (PMID 35977930, 2022). "The correlation between PTK7 expression patterns and cancerization is controversial for cancer lesions in various organs." (PMID 35257502, 2022). "As PTK7 expression is deregulated in a variety of cancer types, a function of PTK7 in cancer is likely." (PMID 34502237, 2021). "CAF-derived POSTN plays a role in cancer stemness via interacting with Protein tyrosine kinase 7 (PTK7) in HNSCC26." (PMID 33739025, 2021).
cancer (continued). "An example of such MOFs is the development of ZnZr-based bimetallic MOFs by using MOF-on-MOF techniques, and it was testified as aptasensor scaffolds for sensing cancer marker protein tyrosine kinase-7 (PTK7)." (PMID 35011330, 2021). "The nanosystem was effectively utilized to release DOX to protein tyrosine kinase 7 (PTK7)-overexpressing cancer cells in a controllable manner, by reacting simultaneously to NIR irradiation and to the acidic intracellular environment." (PMID 33557177, 2021). "Based on our previous studies, an aptamer probe Sgc8-c-Alexa647 is a promising tool for the molecular imaging of PTK7, which is an interesting biomarker in cancer." (PMID 35056072, 2021). "While regulating the EMT, POSTN plays a role in cancer stemness via interacting with protein tyrosine kinase 7 (PTK7) and propagates the cancer stem cell (CSC)-like phenotype via PTK7-Wnt/β-Catenin signalling." (PMID 33739025, 2021). "In head and neck small cellular cancer, CAF-secreted periostin bound PTK7, a receptor expressed on cancer cell surface, favoring CSC invasion and proliferation through the activation PTK7–Wnt/β-Catenin signaling pathway." (PMID 34354950, 2021). "Based on our previous studies, the aptamer probe Sgc8-c-Alexa647 is a promising tool for molecular imaging of PTK7, which is an interesting biomarker in cancer." (PMID 35056072, 2021). "Some specific types of cancer, such as human oesophageal squamous cell carcinoma and T-cell acute lymphocytic leukaemia, were shown to have much higher expression levels of PTK-7." (PMID 34513619, 2021). "Previous studies documented that PTK7 is overexpressed in multiple types of solid cancer, and more significantly, its expression is enriched in TICs/CSCs from PDXs or cancer cell lines." (PMID 34475869, 2021). "Protein tyrosine kinase 7 (PTK7) is a highly conserved receptor tyrosine kinase involved in the Wnt signaling pathway and is overexpressed in multiple cancer types, including NSCLC." (PMID 34238332, 2021). "Protein tyrosine kinase 7 (PTK7) membrane receptor was reported to participate and up-regulate in the progression of various cancers, including hematological malignancies." (PMID 33717084, 2021). "PTK-7, a component of a complex signaling network of the wnt pathway that is considered to be dysregulated in various types of cancer, was found to be highly overexpressed in tumor specimens compared with normal tissue samples in most published data." (PMID 31820857, 2020). "Sgc8-aptamer was chosen for modification with SNs because it showed a high affinity to a cancer-related target, PTK7, with the binding constant in the nanomolar range." (PMID 31941078, 2020). "The receptors that are overexpressed in cancer cells (for example HER2 or protein tyrosine kinase 7 (PTK7)) are the main targets of the aptamers in the therapy." (PMID 31137893, 2019). "Roles for PTK7 in cancer cell invasion have been reported in several clinical and experimental studies, suggesting that PTK7 represents a potential therapeutic target in advanced‐stage type 2 PRCC." (PMID 31361072, 2019). "One protein found to be upregulated in ESCC4 and other cancers, such as colorectal cancer, is protein tyrosine kinase 7 (PTK7)." (PMID 29867084, 2018). "After confirmatory experiments, PTK7, a transmembrane receptor commonly found on cancer cells, was finally identified and verified as the target biomarker." (PMID 29425173, 2018). "In a similar study, a DNA aptamer against protein tyrosine kinase 7 (PTK7), a protein overexpressed in multiple human cancers, was reportedly immobilized on a microfluidic surface." (PMID 30208607, 2018). "On the contrary, overexpression of PTK7 downregulated E-cadherin and promoted cancer cell invasions." (PMID 28545451, 2017). "To further test the role of PTK7 in cancer cell viability, we analyzed apoptosis of siPTK7 and siControl cells by flow cytometry." (PMID 28545451, 2017).
cancer (continued). "Although dysregulation of PTK7 has been reported in some cancers, its role in tumorigenesis and oncogenic progression awaits further demonstration." (PMID 28545451, 2017). "The connection between PTK7 and cancer has so far mostly been deduced on the basis of up- or downregulation of PTK7 in a variety of cancer types." (PMID 28424771, 2017). "Despite being a pseudokinase, PTK7 is considered as a potentially important prognostic marker for many cancers." (PMID 28545451, 2017). "Taken together, these findings suggest that Ptk7 is a highly regulated, polarity-determining molecule in a variety of cellular behaviors both during development and in cancers." (PMID 27438854, 2016). "For example, PTK7 is a catalytically inactive receptor tyrosine kinase which is upregulated in many common human cancers." (PMID 28180111, 2016). "Taken together, these findings emphasize that Ptk7 plays critical roles not only during embryonic development but also in the maintenance of tissue homeostasis and cancer." (PMID 27438854, 2016). "We propose that future studies focused on delineating the signaling machinery downstream of Ptk7 and Mcc will provide new, hitherto unanticipated drug targets to combat cancer metastasis." (PMID 27438854, 2016). "In a xenograft mouse of HCT15 cells, downregulation of PTK7 led to reduced tumor growth, whereas its overexpression in PTK7-negative cancer cells led to increased metastatic events." (PMID 25962058, 2015). "Protein Tyrosin Kinase 7 (PTK7) is upregulated in several human cancers; however, its clinical implication in breast cancer (BC) and lymph node (LN) is still unclear." (PMID 24409301, 2014). "There have been several reports about the upregulation of PTK7 expression in different types of cancer such as pulmonary adenocarcinoma, gastric and breast carcinoma but none about its oncogenic potential." (PMID 24409301, 2014). "Moreover, their potential integration into ADC platforms enhances their versatility as treatments for refractory PTK7-positive cancers, including TNBC." (PMID 39936972, 2025). "Connections: This pattern suggests that BCL3 and PTK7 may enhance cancer progression under varying deuterium levels, potentially complicating the anti-cancer effects of DDW." (PMID 41303451, 2025). "Here, we summarize in chronological order the results of recent research on PTK7 in cancer therapy." (PMID 39474113, 2024). "As for the role played by PTK7, it has been shown that PTK7 could enhance cancer cell adhesion by stabilizing NDRG1, and the PTK7-NDRG1 axis is recognized as a key factor in the development of resistance to AZD9291 (osimertinib) in lung adenocarcinoma cells." (PMID 39474113, 2024). "While PTK7-based treatment modalities have faced challenges in the past, particularly in the era before cancer immunotherapy became mainstream, advancements in specific recognition, drug delivery, and physical therapy using PTK7-targeted aptamers have the potential to revolutionize cancer treatment." (PMID 39474113, 2024). "Notably, PTK7-based cancer diagnostics have become increasingly effective in recent years with advancements in molecular diagnostic techniques." (PMID 39474113, 2024). "In addition, bimetallic ZnZr-MOF with core-shell structure was also fabricated by seeding method and employed as an aptamer sensor platform for the detection of cancer marker protein tyrosine kinase-7 (PTK7)." (PMID 38534224, 2024). "Of course, the data presented here are based on incomplete statistics, but the research activity surrounding PTK7 in various cancer types seems to align with the incidence and research focus on specific cancer types, indicating that PTK7 has been extensively studied in a variety of cancers." (PMID 39474113, 2024). "Moreover, investing in cancer molecular diagnostics and imaging will enhance the utilization of PTK7’s unique properties in cancer treatment." (PMID 39474113, 2024).
cancer (continued). "However, the interplay between PTK7 and Wnt signaling diverges across different cancer and disease contexts." (PMID 38740744, 2024). "Fcγ receptor III (CD16) of NK cells and L-selectin (CD62L) of T cells can be targets of aptamers for recruiting immune cells, and membrane receptors overexpressed in cancer cells, such as PTK7 and c-Met or PD-L1, an immune checkpoint, can be targets of aptamers for binding to cancer cells." (PMID 39407665, 2024). "Furthermore, abundant expression of PTK7 has been detected in the vast majority of primary cancer samples; yet a comprehensive exploration of its deregulation along the entire tumorigenesis process is missing." (PMID 38773263, 2024). "PTK7, a pseudo tyrosine kinase lacking catalytic activity, is involved in the occurrence and development of a variety of cancers and is associated with cell survival, growth, and migration." (PMID 39588545, 2024). "Finally, we will explore the performance of PTK7 in cancer diagnosis, treatment, and prognostic assessment to evaluate its value in the clinical management of cancer." (PMID 39474113, 2024). "PTK7 is of interest in the cancer biology field as it is often found dysregulated in cancer." (PMID 38474329, 2024). "Further, they also showed that PTK7 increased the stiffness of the cancer stroma." (PMID 38468988, 2024). "PTK7, involving both Wnt and VEGF signaling, is associated with cancer drive and repression." (PMID 37190019, 2023). "On the other hand, we wondered whether miR‐503 regulates cancer invasiveness only through the target inhibition of PTK7." (PMID 37212485, 2023). "The potential role of PTK7 in tumorigenesis has been documented in different cancers, including BC." (PMID 37569547, 2023). "PTK7 localized to the cytoplasm and cytomembrane in cancer cells." (PMID 35257502, 2022). "Therefore, we propose that PTK7 mAbs can be used as lead molecules to develop humanized PTK7 antibodies as novel therapeutics for PTK7-positive cancers, including ESCC." (PMID 36293051, 2022). "Therefore, PTK7 is a biomarker and a therapeutic target molecule for various cancers, including ESCC." (PMID 36293051, 2022). "Furthermore, a xenograft tumor model using KYSE-30 cells can be used to analyze PTK7-targeted anti-cancer drugs and the role of PTK7 in vivo." (PMID 35216506, 2022). "PTK7 is upregulated in various cancer types, including ESCC." (PMID 35216506, 2022). "In addition, this xenograft tumor model of KYSE-30 cells can be used to analyze anti-cancer agents targeting PTK7 and the role of PTK7 in vivo." (PMID 35216506, 2022). "In our study, the high conservation of the affected region, the high alteration frequency of PTK7 in several cancers, and its postulated oncogenic function based on recent literature prompted us to prioritize the PTK7V354M variant for further functional validation." (PMID 35163215, 2022). "After being loaded with DOX, these exosomes could efficiently deliver DOX to cancer cells overexpressing PTK7 and thus exert their anti-cancer effects." (PMID 35155421, 2022). "Thus, a better understanding of the molecular function of PTK7 in cancer development in general and cancer-related pathways in particular requires further experimental investigation." (PMID 35163215, 2022). "In addition, the correlation between PTK7 expression and cancer invasion/metastasis and prognosis has been found to vary by organ and tumor types." (PMID 35257502, 2022). "Overexpressions of ROR1, ROR2, and PTK7 have been detected in numerous cancers." (PMID 35504983, 2022). "Calcitriol increases the expression of stemness-related genes, such as the leucine-rich repeat-containing G protein-coupled receptor 5 (LGR5), SMOC2, LRIG1, MEX3A, MSI1, and PTK7, attenuating the transformation into cancer stem cells, and, therefore, impacts tumorigenesis at a very early stage." (PMID 36364774, 2022). "PTK7 has been shown to be involved in vertebrate embryogenesis and epithelial‐mesenchymal transition which plays an important role in cancer." (PMID 35257502, 2022).
cancer (continued). "Another studies also found that cleavage of PTK7 by MT1-MMP could affect cancer cell motility and metastasis through the regulation of cell protrusions." (PMID 33947097, 2021). "The immunosensors for cancer detection can be developed for either cancer markers, for example protein tyrosine kinase 7 (PTK7) that is overexpressed in the membrane of leukemic Jurkat cells, for prostate specific antigen (PSA), or for circulating tumor cells (CTC)." (PMID 34073054, 2021). "Research with human fibrosarcoma HT1080 cells also suggested that cleavage of PTK7 by MT1-MMP could affect cancer cell migration and metastasis through the regulation of cell protrusions, including lamellipodia and invadopodia." (PMID 33947097, 2021). "In addition, our present data demonstrated that loss of PTK7 expression in TNBC cells results in a downregulated EGFR/Akt signaling and reduced tumor growth in MBA-MD-468 TNBC cancer xenografts." (PMID 34367983, 2021). "In this case, the aptamer selective to the PTK7 cancer marker and anti-PTK7 antibodies can be used." (PMID 34073054, 2021). "PTK7 is overexpressed and contributes to thyroid and cervical cancer progression." (PMID 34367983, 2021). "Further research is required to dissect the molecular and cellular mechanisms by which PTK7 controls CIL and may help us to use PTK7 as a tool to target cancer invasion." (PMID 34502237, 2021). "Recent evidence has shown that PTK-7 expression levels are increased in some tumor types and may be a potential target in cancer management." (PMID 31820857, 2020). "The mechanism of action remains controversial with WNT and non-canonical functions proposed, but the use of PTK7 in cancer treatment could well be under way." (PMID 31382613, 2019). "PTK7 was originally discovered as a colon carcinoma kinase-4 upregulated in cancer tissue." (PMID 31382613, 2019). "Moreover, PTK7 is significantly upregulated from localized to advanced‐stage type 2 PRCC and is linked to cancer cell invasion." (PMID 31361072, 2019). "Therefore, PTK7-targeted therapy should be applied to only for cancers with either low PTK7 expression or where the inhibition of PTK7 has been shown to reduce tumorigenicity." (PMID 29867084, 2018). "The oncogenic role of PTK7 has been reported in various cancer cells including ESCC cells." (PMID 29867084, 2018). "We analyzed RNA-seq data from TCGA to assess PTK7 mRNA levels in various cancer tissues." (PMID 29867084, 2018). "In contrast, PTK7 may also function as a tumor suppressor, as it is downregulated in other cancers such as melanoma and clear cell renal cell carcinoma." (PMID 29867084, 2018). "As we have previously demonstrated, upregulation of PTK7 may indicate that it is an important target for pediatric cancers." (PMID 29099739, 2017). "Additionally its function in adult tissue homeostasis is demonstrated by the fact that misregulation of PTK7 expression correlates with development of cancer and its progression to metastasis in various cellular contexts." (PMID 28424771, 2017). "Thus, attenuation of PTK7 function would be a valuable therapeutic means to control ESCC and other cancers that express PTK7." (PMID 27689325, 2016). "PTK7 enhances proliferation, survival, and migration of various cancer cells." (PMID 27689325, 2016). "PTK7 and Ror2 expression is frequently deregulated in a variety of cancers." (PMID 26680417, 2015). "Notwithstanding this debate, anti-tumor effects observed when depleting PTK7 expression, as exemplified in our study as in others, indicate that it may represent a valuable target for different cancer therapeutics including CRC." (PMID 25962058, 2015). "PTK7 plays an important role in the motility and invasivity of cancer cells." (PMID 24987951, 2014). "It is tempting to hypothesize that the activation of CREB by the C-terminal PTK7 fragments contributes to both normal embryogenesis and cancer." (PMID 24618420, 2014).